CD4 (CD4 molecule)
Diseases named in the same sentence as CD4 in open-access papers (continued):
Sharing a sentence is not in itself a finding about the gene and the disease.
H1N1 influenza (7 papers, 2008 to 2025). "The potential for cross-reactive CD4 T cells has been found in many studies, including those that investigated CD4 T cell immunity when a novel pandemic H1N1 influenza strain emerged in 2009." (PMID 36851752, 2023). "In order to measure the degree of T-cell activation during 2009 pandemic H1N1 virus infection, we assessed the percentage of CD4+ and CD8+ cells that expressed the activation markers CD38/HLA-DR." (PMID 21625541, 2011). "The pandemic H1N1 influenza in 2009 (A/California/04/09, CA/09) is a novel quadruple reassortant that provided the opportunity to assess the functional quality of newly formed memory CD4 T cells in the adult human population." (PMID 23526940, 2013). "Blood monocytes, CD4+ and CD8+ T-cell count in 13 patients with pandemic H1N1 influenza and 13 healthy controls." (PMID 21625541, 2011). "The results indicated a reduction in CD4 and CD8 T cell counts in about half of the patients during the early stage of 2009 H1N1 virus infection, which was similar to previous reports in China." (PMID 20513239, 2010).
Hypercalcemia (7 papers, 2010 to 2026). An abnormally increased calcium concentration in the blood. "Hypercalcemia was rare, affecting 1 B‐cell case and 1 CD4+ T‐cell case." (PMID 31693230, 2020).
hypereosinophilic syndrome (7 papers, 2007 to 2024). Hypereosinophilic syndrome (HES) constitutes a rare and heterogeneous group of disorders, defined as persistent and marked blood eosinophilia and/or tissue eosinophilia associated with a wide range of clinical manifestations reflecting eosinophil-induced tissue/organ damage. "Interestingly, the CD4+ Th2 cells found in a condition related to IgG4-RD and called “lymphocytic variant of human hypereosinophilic syndrome” are reminiscent of activated LatY136F CD4+ T cells in that they express low levels of TCR at their surface and primarily respond to CD28 signals." (PMID 37624388, 2023). "Case LYWS-1394 (Valentina Tabanelli) was a classic example of a lymphoid variant of hypereosinophilic syndrome (L-HES) in a 51-year-old man with a unilaterally enlarged tonsil and a 13-year history of eosinophilia and an aberrant CD4(+), sCD3(-) T-cell population in the peripheral blood." (PMID 37500795, 2023).
hypersensitivity reaction (7 papers, 2015 to 2025). "Herpes-associated EM (HAEM) is a hypersensitivity reaction in which CD4+Th1 cells produce IFN-γ (interferon-gamma)." (PMID 37908411, 2023). "This type of reaction is subdivided into types IVa (the classic hypersensitivity reaction), IVb, IVc, and IVd and is due to CD4+ T helper-1 (Th1) cell responses to antigens presented by antigen-presenting cells (APCs)." (PMID 40142183, 2025). "A delayed hypersensitivity reaction, in which the offending drug particularly activates CD4 and CD8 T cells to overproduce cytokines and acute phase reactants, is one of the various causes causing DRESS that have been proposed." (PMID 39583406, 2024). "Neutrophil recruitment to the airway during allergic sensitization alters the expansion and function of CD4+ T cells." (PMID 35191395, 2022). "OLR may be a delayed hypersensitivity reaction, in which helper CD4 T and cytotoxic CD8 T lymphocytes act by releasing cytokines (TNF-α and IFN-δ), which activate pro-inflammatory cells resulting in tissue damage." (PMID 36397025, 2022). "Skin sensitization is primary associated with induction of Th1 cells, promoting a cytotoxic CD8+ T-cell response and secretion of IL-2 and interferon (IFN)-γ, while respiratory sensitization generally involve CD4+ Th2 cells and are characterized by high levels of IL-4, IL-10 and IL-13." (PMID 25760038, 2015). "OLR may be a delayed hypersensitivity reaction in which CD3+, CD4+, and CD8 + lymphocytes are involved." (PMID 36397025, 2022).
hypogonadism (7 papers, 2011 to 2025). A disorder characterized by decreased function of the gonads. "There was a significant association of hypogonadism with older age, herbal medicine use, weight loss, advanced clinical stage, CD4+ count, and decreased libido." (PMID 38476640, 2024). "Interestingly, when the whole population was considered, the prevalence of hypogonadism was inversely correlated with CD4+ cell count and year of publication." (PMID 34440836, 2021). "CD4 level was significantly lower among study group participants with hypogonadism than among study group without hypogonadism (Two-sample Wilcoxon rank-sum (Mann-Whitney) test; p = 0.0311)." (PMID 38654196, 2024). "The findings also show a significant decrease in the levels of CD4 count among HIV patients with hypogonadism as compared with those without hypogonadism This is similar to the finding of the previous study." (PMID 38654196, 2024). "Univariate analysis, CD4+ count (COR 0.6; 95% CI 0.3–1.2; p = 0.136), and hypogonadism (COR 1.9; 95% CI 1.3–2.9; p = 0.003) were not subjected to multivariate logistic regression analysis due to collinearity with WHO clinical stage and Testosterone (TT) respectively." (PMID 41035487, 2025). "Similarly, the current study showed significantly reduced CD4 count that represents a marker of advanced HIV infection and poor health status, in HIV patients with hypogonadism than HIV patients without hypogonadism." (PMID 38654196, 2024).
kidney tumor (7 papers, 2011 to 2023). "Alphataxin treatment increased the CD4/CD8 ratio and the number of CD4+ TILs in murine orthotopic kidney tumors." (PMID 34900690, 2021). "We performed RNA-sequencing (RNAseq) analysis on RNA extracted from M1 and M2 cells isolated from kidney tumors and splenic CD4+ T cells." (PMID 25264896, 2014). "We demonstrate here that Ad5mTRAIL+CpG, given at the primary renal tumor site, leads to infiltration of tumor-bearing kidneys by effector CD4 and CD8 T cells." (PMID 22312440, 2012). "Intra-renal administration of Ad5mTRAIL+CpG on day 7 led to an influx of effector phenotype CD4 and CD8 T cells into the kidney by day 12 and regression of established primary renal tumors." (PMID 22312440, 2012). "With the kidney tumor of Bird 3, the CDR3 spectra of cultured cells included a dominant peak of identical length to that in CD4+ T cells but also included a second slightly shorter peak." (PMID 21573129, 2011). "Depletion of CD4 cells led to a slight increase in primary renal tumor size as compared to non-depleted mice, but this difference was not statistically significant (p = 0.14)." (PMID 22312440, 2012). "As a common motif, nonlymphoid (liver, kidney tumor, lung) but not lymphoid (bone marrow, spleen) tissues were characterized by significantly elevated frequencies (or a clear trend thereof in the case of lung) of spike-specific CD4+ T cells over those quantified in blood." (PMID 37815874, 2023).
lower respiratory tract infections (7 papers, 2017 to 2025). "Respiratory syncytial virus (RSV) causes lower respiratory tract infections in infants and young children, leading to a pathogenesis-associated imbalance in CD4+ T-cell subsets and monocyte subsets." (PMID 39656009, 2025). "HAd5 is an intracellular pathogen that usually causes upper and lower respiratory tract infections, controlled by efficient polyfunctional CD4 and CD8 T-cell responses (37, –, 39), leading to persistent sub-clinical infections in most of immunocompetent individuals." (PMID 30541853, 2019). "Ongoing myeloid cell infection may seeds epithelial infection in some settings, but the main cell type supporting chronic lung infection in CD4+ T cell-deficient mice was myeloid." (PMID 28394921, 2017). "One patient died 5 days after the date of CD4 testing after presenting to hospital with a clinical diagnosis of a lower respiratory tract infection; no central nervous system infection was suspected, and the patient did not receive a lumbar puncture as part of his diagnostic evaluation." (PMID 33087436, 2020).
lymphoid tumors (7 papers, 2011 to 2023). "Marek’s disease virus (MDV) is an oncovirus that induces lymphoid tumors in susceptible chickens, and may affect the epigenetic stability of the CD4 gene." (PMID 21645322, 2011). "TFH, a distinct subset of CD4+ cells, whose functions in cancers are rarely reported, seems to act as a protector in non-lymphoid tumors and hazardous factor in lymphoid tumors." (PMID 33643915, 2020). "One notable difference to cells expressing MYC alone was that the double positive CD4+CD8+ lymphoid tumor cells population was diminished among FLIPL/MYC-expressing cells in favor of the CD4+ population." (PMID 22393362, 2012). "The following surface antigens were selected for analysis: for myeloid tumors: MV-4-11, Thp-1, HL-60—CD11b, CD14, K562 and KG-1—CD34, and CD38; for lymphoid neoplasms: Raji, Daudi, U2932—CD19, CD20, Jurkat—CD4, CD8." (PMID 35053549, 2022). "Previous experiments demonstrated that CD4+/CD25+ T lymphocytes have a regulatory function on tumor-reactive cytotoxic T lymphocytes and thereby successfully suppress lymphocytic tumor rejection." (PMID 26871598, 2016).
metastatic colorectal cancer (7 papers, 2010 to 2025). "Our data confirms previous clinical reports of the increased number of CD8+ and CD4+ T cells in metastatic colorectal cancer patients following Bevacizumab treatment." (PMID 40650058, 2025). "Within a clinical phase I/II combined chemoimmunotherapy trial of patients with metastatic colorectal cancer we assessed frequencies of FOXP3-expressing CD4+CD25high Treg cells in peripheral blood before initiation of therapy in comparison to healthy controls." (PMID 22276195, 2012). "We also showed that responding bevacizumab-treated patients reported a higher percentage of circulating CD4 effector T cells compared with nonresponding bevacizumab patients, confirming what has already been observed in metastatic colorectal cancer." (PMID 30889935, 2019).
Myalgia (7 papers, 2015 to 2025). "Polymyalgia rheumatica patients were shown to have a higher percentage of IL-2 and IFNγ producing CD4+ T cells in response to VZV stimulation using flow cytometry." (PMID 29118757, 2017). "Increases in CD4+ and CD8+ T cells were observed with moderate side effects of myalgia and flu-like syndrome and the rise of CD4+ T cells was shown to sustain for at least 28 days after the last infusion." (PMID 25606813, 2015). "Interestingly, arthralgia, myalgia and fatigue occurring at the time of study were associated with a higher proportion of CD8+ IFNγ and CD4+ IL-2-secreting cells, while headache was associated with higher CD4+ IL-2 and IFNγ ELISpot responses." (PMID 33679690, 2020). "Symptoms of arthralgia, myalgia, and fatigue occurring at the time of sampling were significantly associated with a higher proportion of CD8+ IFNγ and CD4+ interleukin (IL) 2–secreting cells, while headache was associated with higher CD4+ IL2 and IFNγ ELISpot response." (PMID 31784751, 2020). "Headache, fatigue, myalgia, and arthralgia were associated with the magnitude of T-cell response to pooled GP peptides, with higher CD4+ production of IL2 and CD8+ production of IFNγ, but not with antibody responses." (PMID 31784751, 2020). "Comprised of participants reporting myalgia/arthralgia at 12 months and distinguished by lower total lymphocytes with reduced CD3+, CD3+CD4+, and CD19+ counts, suggesting a broader low-grade immune insufficiency rather than isolated activation." (PMID 41472279, 2025). "Increased production of IFN-γ and perforin by CD4+CD28− T cells has been shown not only in RA but also in AS, polymyalgia rheumatica/giant cell arteritis, granulomatous polyangiitis, and abdominal aortic aneurysms." (PMID 25834833, 2015). "Furthermore, NKG2D was also expressed on CD4+CD28− T cells in giant cell arthritis and polymyalgia rheumatica, accumulating around the vasa vasorum in the temporal arteries suggesting a ligand interaction in this region." (PMID 25834833, 2015).
myelodysplastic syndrome (7 papers, 2016 to 2023). A clonal hematopoietic disorder characterized by dysplasia and ineffective hematopoiesis in one or more of the hematopoietic cell lines. "Increased amount of Treg (CD4+ CD25hi Foxp3+) was also identified in patients with myelodysplastic syndrome (MDS), correlating with high-risk MDS and higher number of blasts in the BM." (PMID 33801964, 2021).
nephrotic syndrome (7 papers, 2013 to 2026). A collection of symptoms that include severe edema, proteinuria, and hypoalbuminemia; it is indicative of renal dysfunction. "An increase of CD4+CD25 + cells and CD4+CD25 + FoxP3+ Treg cells in peripheral blood after DD for rituximab has been described in a successful procedure in a patient suffering from nephrotic syndrome." (PMID 33424601, 2020). "In our study, low CD4+ T lymphocyte count was identified as a significant predictor of PCP mortality among nephrotic syndrome patients." (PMID 32148596, 2020). "• Patients with MN and nephrotic syndrome presented a CD4+/CD8+ ratio greater than the control group due to a reduction of CD8+ T cell subset." (PMID 31788474, 2019). "The number and proportion of CD4 + T cells in patients with nephrotic syndrome remained unchanged." (PMID 34158604, 2021). "Decreased CD4+ T lymphocyte count could be a useful predictor of PCP mortality among nephrotic syndrome patients, which can be easily used clinically." (PMID 32148596, 2020). "Co-culture with CD4+CD25+CD127low UCB-Tregs also decreased the percentage of CD56+ NK cells in the SLE-PBMC population, implicated in excessive IFN-γ production in patients with active SLE, where elevated levels of IFN-γ have been shown to be associated with nephrotic syndrome." (PMID 37736101, 2023).
Neuromyelitis Optica Spectrum Disorder (7 papers, 2015 to 2022). "For example: (i) in the presence of neuromyelitis optica immunoglobulin G, astrocyte‐destructive lesions can be initiated by CD4+ T cells when these cells recognize aquaporin 4 (AQP4), but also when they recognize other antigens of the central nervous system." (PMID 28344667, 2017). "The homeostatic balance between production and elimination of CD4+ T cells in peripheral blood plays an important role in patients with neuromyelitis optica (NMO)." (PMID 28174515, 2017). "Similarly to us, others recently found that CD4+ T cells, and more specifically Th17 and Th22 cells, of MS and neuromyelitis optica (NMO) patients secreted more IL-22 than those of HC." (PMID 26077779, 2015).
ocular infection (7 papers, 2013 to 2024). "Past studies showed that CD4+ T cells cause damage to the cornea by producing proinflammatory cytokines and promoting infiltration of leukocytes to the cornea late in ocular infection." (PMID 32398314, 2020). "In mice, CD4 T cells appear in the corneas around day 6 post-ocular infection with HSV-1 and their numbers continue to increase during the latter stage of SK development." (PMID 30941142, 2019). "Some studies found that ocular infection of mice with the HSV-1 RE strain mainly induces SK mediated by CD4 T cells, whereas infection of the same stain of mice with HSV-1 KOS show SK which is dependent on CD8 T cells." (PMID 30941142, 2019). "IRU is an exclusion diagnosis that is typically associated with HIV patients receiving HAART who have experienced an increase in their CD4 + T cell count > 100 cells/mm3 and have a new paradoxical inflammation in an eye with a preexisting history of CMVR or other ocular infection." (PMID 38381160, 2024).
oligodendroglioma (7 papers, 2021 to 2025). A well-differentiated (WHO grade II), diffusely infiltrating neuroglial tumor, typically located in the cerebral hemispheres. "In contrast, increases in CD8+ or activated CD4+ T cells and losses of resting NK, mast, or eosinophil subsets emerge only in isolated datasets, likely reflecting cohort‐specific variability or the limited sample size of oligodendrogliomas (n = 14–24)." (PMID 41354084, 2025).
onychomycosis (7 papers, 2009 to 2026). "Conversely, our findings suggest that higher CD4+ cell counts (>400 cells/μL) were associated with dermatophytosis (t = −2.730, p = 0.008), onychomycosis (t = −3.050, p = 0.003), and Pityriasis/Tinea versicolor (t = −3.252, p = 0.001)." (PMID 40943696, 2025). "Similar figures were observed in our study participants, with lower CD4+ T-cell counts being observed in virus-suppressed PLWH with onychomycosis." (PMID 37888218, 2023). "Onychomycosis is more frequent when CD4+ T-cell counts fall to <450 cells/μL and occurs at a prevalence of 20–44% in HIV-infected individuals." (PMID 37888218, 2023). "The mean CD4+ cell count was lower in patients diagnosed with onychomycosis compared to those without onychomycosis (0.38 ± 0.30 vs. 0.49 ± 0.32, p = 0.03), and the prevalence of onychomycosis increased in advanced stages of HIV disease (21% stage A disease, 30% stage B, 54% stage C, p < 0.02)." (PMID 37504701, 2023).
osteonecrosis (7 papers, 2020 to 2025). A none disease characterized by death of bone tissue due to a lack of blood supply. "Recent evidence suggests that abnormalities involving CD4+T lymphocytes are associated with the pathophysiology of osteonecrosis (ON); however, few studies have addressed the CD4+T cells in ON related to sickle cell disease (SCD/ON)." (PMID 33132753, 2020). "In contrast, EM CD4+ activated cells and DP (CD4+ CD8+) T cells were found to be associated with a reduced risk of osteonecrosis." (PMID 39596473, 2024). "The progression of osteonecrosis involves reduced levels of bioactive compounds in peripheral blood mononuclear cells and elevated CD4+T circulating levels to stimulate pro-inflammatory cytokines contributing to inflammation at target site." (PMID 36379523, 2022). "Conversely, there was an increased frequency of either IFN-γ+ or IL-17+CD4+T cells in stimulated BM-MNC of SCD patients with osteonecrosis." (PMID 33132753, 2020). "HIV-infected patients with low baseline CD4+ T cell counts presented with increased osteonecrosis after ART initiation and might have undergone prior AIDS-defining illnesses and the most robust T cell reconstitution." (PMID 40151145, 2025). "The majority of patients with osteonecrosis have obviously restored CD4+ T cell counts post-ART." (PMID 40151145, 2025). "In our principal MR IVW analysis, results indicated that the levels of two count-related immune traits (CD11c + CD62L − monocyte and CM DN (CD4 − CD8 −)) have a negative correlation with the risk of osteonecrosis." (PMID 38654114, 2024). "In this small cross-sectional study, we demonstrated that lower frequency of circulating CD4+, CD8+, and naive T lymphocyte subsets were directly associated with SCD disease but not with osteonecrosis." (PMID 33132753, 2020). "More importantly, the frequencies of IFN-γ+-producing and IL-17+-producing CD4+T cells in stimulated BM-MNCs were significantly higher in SCD/ON patients than controls patients with osteonecrosis not related to SCD." (PMID 33132753, 2020). "We also observed decreased percentage of CD4+ and CD8+ in the bone marrow of patient with osteonecrosis related to SCD in comparison to non-SCD patients." (PMID 33132753, 2020).
Peptic ulcer (7 papers, 2014 to 2024). The term peptic ulcer refers to acid peptic injury of the digestive tract, resulting in mucosal break reaching the submucosa. "Among 52 patients who discontinued CPT, 10 (19.25%) and 14 (26.92%) were due to improvement of CD4 (>350 cells/mm3) and peptic ulcer disease, respectively." (PMID 24507658, 2014). "Most patients discontinued CPT due to peptic ulcer (19.25%) and CD4 improvement (26.92%)." (PMID 24507658, 2014). "In contrast, the proportion of FOXP3+ events among CD4+CD25hi cells was not significantly different with respect to peptic ulcer disease status among the infected group." (PMID 27014260, 2016).